CHSY1 (chondroitin sulfate synthase 1)
Description:
Catalytic component of CHSY1-CHPF2 and CHSY1-CHPF chondroitin sulfate synthase complexes. Has both beta-1,3-glucuronic acid and beta-1,4-N-acetylgalactosamine transferase activity. Transfers glucuronic acid (GlcUA) from UDP-GlcUA and N-acetylgalactosamine (GalNAc) from UDP-GalNAc to the non-reducing end of the elongating chondroitin polymer. Involved in the negative control of osteogenesis likely through the modulation of NOTCH signaling.
Synonyms: ChSy-1; CHSY; CSS1; KIAA0990; TPBS
Tractability: Antibody: UniProt places it where antibodies can reach, with high confidence; its Gene Ontology location is reachable by antibodies, with high confidence; UniProt predicts a signal peptide or a membrane-spanning region. PROTAC: its protein half-life has been measured.
Gene: Protein-coding gene on chromosome 15 (101,175,727 to 101,252,048, reverse strand). Ensembl gene ENSG00000131873.
Subcellular location: Golgi apparatus, Golgi stack membrane; Secreted
Pathways (Reactome):
Disease: Defective CHSY1 causes TPBS
Metabolism: CS-GAG biosynthesis
Gene Ontology:
Molecular function: glucuronosyl-N-acetylgalactosaminyl-proteoglycan 4-beta-N-acetylgalactosaminyltransferase activity; N-acetylgalactosaminyl-proteoglycan 3-beta-glucuronosyltransferase activity; acetylgalactosaminyltransferase activity; glycosyltransferase activity
Biological process: chondroitin sulfate proteoglycan biosynthetic process; negative regulation of ossification; response to nutrient levels
Cellular component: extracellular region; membrane; Golgi membrane; Golgi apparatus; Golgi cisterna membrane
Genetic constraint (gnomAD): Loss-of-function variants: 13 observed, 57.92 expected, observed/expected ratio (o/e) 0.22, 90% interval 0.14 to 0.36. The upper end of that interval is the gene's LOEUF score, 0.36, which puts it in group 1 of 6, group 1 being the genes least tolerant of losing a copy. Missense variants: 940 observed, 1,016.6 expected, observed/expected ratio (o/e) 0.92, 90% interval 0.88 to 0.98. Synonymous variants: 452 observed, 394.02 expected, observed/expected ratio (o/e) 1.15, 90% interval 1.06 to 1.24.
Homologues: Orthologues: macaque CHSY1 (99% identical), dog CHSY1 (97% identical), pig CHSY1 (97% identical), mouse Chsy1 (94% identical), rat Chsy1 (94% identical), tropical clawed frog chsy1 (86% identical), guinea pig CHSY1 (84% identical), rabbit CHSY1 (84% identical), zebrafish chsy1 (78% identical), Drosophila melanogaster Chsy (42% identical), Caenorhabditis elegans sqv-5 (35% identical). Paralogues in human: CHSY3 (68% identical), CHPF (20% identical), CHPF2 (20% identical), CSGALNACT2 (20% identical), CSGALNACT1 (19% identical), B4GALNT4 (19% identical), B4GALNT3 (18% identical).
Diseases named in the same sentence as CHSY1 in open-access papers:
CHSY1 is named in the same sentence as 36 diseases in open-access papers, as found by Europe PMC text mining. Sharing a sentence is not in itself a finding about the gene and the disease. The quoted sentences say what the papers report.
colorectal cancer (8 papers, 2015 to 2025). A primary or metastatic malignant neoplasm that affects the colon or rectum. "CHSY1 exacerbates colorectal cancer metastatic progression by inducing CD8+ T cell exhaustion via the succinate metabolism pathway." (PMID 39461979, 2024). "Targeting CHSY1 with artemisinin, in conjunction with anti-PD-1 therapy, significantly reduces colorectal cancer liver metastasis." (PMID 39461979, 2024). "CHSY1 is also upregulated in other types of solid tumor, including hepatocellular carcinoma, colorectal cancer, and soft tissue sarcomas." (PMID 32019907, 2020). "In addition, CHSY1 has been reported to suppress apoptosis in colorectal cancer and promote migration in HCC." (PMID 36923282, 2022). "Chondroitin sulfate synthase 1 (CHSY1), one of glycosyltransferases, exhibits oncogenic features, promoting the progression of hepatocellular and colorectal cancers and activating the hedgehog signaling pathway and the NF-kappa-B and/or the caspase-3/7 signaling pathways." (PMID 34681854, 2021). "The carcinogenic effects of Chondroitin sulfate synthase 1 (CHSY1) have been reported in a variety of human cancers, such as gastric cancer, colorectal cancer, and hepatocellular carcinoma." (PMID 40570725, 2025).
hepatocellular carcinoma (8 papers, 2020 to 2025). A malignant tumor that arises from hepatocytes. "Specifically, upregulation of CHSY1 has been implicated in promoting the proliferation and metastasis of various cancers including gastric cancer, hepatocellular carcinoma, glioblastoma and other tumors." (PMID 38812506, 2024). "Chondroitin sulfate synthase 1 (CHSY1), the enzyme that mediates the polymerization step of chondroitin sulfate, is a critical mediator of malignant character in hepatocellular carcinoma, also exerts its function via activating Hedgehog signaling pathway." (PMID 41346572, 2025). "Recent studies have reported that CHSY1 was overexpressed in various tumors (for example, hepatocellular carcinoma, glioma, soft tissue sarcomas), demonstrating its possible association with tumor progression." (PMID 37749638, 2023). "CHSY1 was also found to be able to regulate hedgehog signaling, thus promoting the malignant behaviors of cancer cells of hepatocellular carcinoma." (PMID 37710286, 2023). "CHSY1 overexpression in hepatocellular carcinoma promotes cancer cell growth, migration, invasion and EMT through the hedgehog signalling pathway." (PMID 35571047, 2022). "CHSY-1 enhanced SHh binding to the cell surface of hepatoma cells, co-localized with chondroitin sulfate, and promoted pulmonary metastasis in a mouse xenograft model." (PMID 33440657, 2021).
glioma (5 papers, 2020 to 2023). A benign or malignant brain and spinal cord tumor that arises from glial cells (astrocytes, oligodendrocytes, ependymal cells). "CHSY1 expression in glioma tumors is positively associated with adverse clinicopathologic factors and is a predictor of poor survival." (PMID 32019907, 2020). "According to REMBRANDT database, high expression of CHSY1 is associated with poor overall survival in glioma patients (n = 329, p = 5.9E – 7)." (PMID 32019907, 2020). "Using a chondroitin sulfate-specific antibody, we showed that the expression of CHSY1 was significantly associated with CS formation in glioma tissue and cells." (PMID 32019907, 2020). "Here we demonstrated that CS56 staining is moderately associated with CHSY1 expression in human glioma tissue (rs = 0.676), suggesting that other CS modification enzymes, such as DSE and CHSTs, may also modulate CS56 epitopes." (PMID 32019907, 2020). "Silencing or overexpression of the major CS synthase, chondroitin sulfate synthase 1 (CHSY1), significantly regulated the glioma cell invasive phenotypes and modulated integrin expression." (PMID 34944101, 2021). "Our study so far revealed that the critical CS synthase, CHSY1, regulates the expression of integrins and cell invasive phenotypes in glioma cells." (PMID 34944101, 2021). "Our previous studies have identified that CHSY1 is frequently upregulated in tumor tissues such as human glioma and hepatocellular carcinoma." (PMID 34944101, 2021). "Taken together, these results provide information on CHSY1 expression and its role in glioma progression, and highlight novel insights into the significance of CHSY1 in PDGFRA signaling." (PMID 32019907, 2020). "Inhibiting PDGFR activity with crenolanib decreased CHSY1-induced malignant characteristics of GL261 cells and prolonged survival in an orthotopic mouse model of glioma, which underlines the critical role of PDGFRA in mediating the effects of CHSY1." (PMID 32019907, 2020). "We explore the changes of cell surface CS and its contribution to malignant growth of glioma cells, by manipulating CS Synthase 1 (CHSY1) expression." (PMID 32019907, 2020). "In this study, we showed that CHSY1 is not only a prognostic factor for poor survival of glioma patients but that it also activates the PDGFRA pathway to promote tumorigenesis." (PMID 32019907, 2020). "To develop novel strategies for treating this fatal disease, we explored the role of CHSY1 in glioma and its potential as biomarker." (PMID 32019907, 2020). "Spearman’s rank test revealed that expression of CHSY1 was positively correlated with CS56 intensity (p = 1.22E − 12, rs = 0.676), indicating that CHSY1 is one of the mediators of CS56 immunoreactivities in glioma tissue." (PMID 32019907, 2020). "Our data indicates that CHSY1 is frequently upregulated in human glioma, particularly in GBM, suggesting the potential for VAR2SCA targeting." (PMID 32019907, 2020). "Together, these data suggest that CHSY1 is frequently upregulated in glioma patients, and that its expression correlates with the worst histologic grade and poor overall survival." (PMID 32019907, 2020). "To examine CHSY1 protein expression in human glioma, we carried out immunohistochemistry on glioma tissue array containing 85 primary glioma tissues." (PMID 32019907, 2020). "Chondroitin sulfate synthase 1, CS polymerization enzyme, has been significantly upregulated in GBM compared to normal brain tissue, and chondroitin sulfate synthase 1 mediates the increase of 6-O sulfation of CS in human glioma, supporting our finding of elevated 6-O CS sulfation in GBM samples." (PMID 35202840, 2022). "We thus hypothesized that targeting CS chains by knockdown of CHSY1 or treating glioma cells with C6S binding peptides may result in decreased CD44 protein levels, and inhibit the outside-in signals from regulating the gene expression of integrins." (PMID 34944101, 2021).
glioma (continued). "Moreover, we tested the CS-specific binding peptide, resulting in the suppression of glioma cell mobility in a fashion similar to that observed upon the silencing of CHSY1." (PMID 34944101, 2021). "Intriguingly, under our staining conditions, no obvious CHSY1 signal was observed in the normal brain tissue (n = 5), whereas 85% of grade IV GBM tissues expressed high levels (+2 and +3) of CHSY1, which is significantly higher than that in low-grade glioma and normal brain tissue." (PMID 32019907, 2020). "We performed database analysis and immunohistochemistry on human glioma tissue, to demonstrate that the expression of CHSY1 was frequently upregulated in glioma, and that it was associated with adverse clinicopathologic features, including high tumor grade and poor survival." (PMID 32019907, 2020). "CHSY1 was expressed in the paranuclear cytoplasm of the majority of glioma tissues." (PMID 32019907, 2020). "In addition, overexpression of CHSY1 in glioma cells enhanced cell viability and orthotopic tumor growth, whereas CHSY1 silencing suppressed malignant growth." (PMID 32019907, 2020). "CHSY1 promotes malignant growth in multiple GBM cell lines in vitro and in a mouse orthotopic glioma model." (PMID 32019907, 2020). "Mechanistic investigations revealed that CHSY1 selectively regulates PDGFRA activation and PDGF-induced signaling in glioma cells by stabilizing PDGFRA protein levels." (PMID 32019907, 2020). "We have previously demonstrated that CHSY1 functions as the dominant CS synthase in human glioma cells, and its expression is significantly correlated with the anti-CS antibody (CS56) staining intensity in glioma tissues." (PMID 34944101, 2021). "Moreover, the key CS synthase, CHSY1, regulates the expression of integrins and modifies CS chains on CD44 in glioma cells." (PMID 34944101, 2021). "In our orthotopic glioma model, Cre treatment significantly enhanced survival of mice transplanted with CHSY1-overexpressing cells, whereas no obvious response to the treatment was seen in the mock-transfected group." (PMID 32019907, 2020). "Although detailed mechanisms underlying these effects are yet to be elucidated, these findings imply that aberrant expression of GAG synthases, such as CHSY1, could provide a molecular basis for targeting PDGFRA pathway in glioma." (PMID 32019907, 2020). "Furthermore, we identified CD44 as a crucial chondroitin sulfate proteoglycan (CSPG) that was modified by CHSY1 on glioma cells, and the suppression of CS formation on CD44 by silencing the CHSY1-inhibited interaction between CD44 and integrin β1 on the adhesion complex." (PMID 34944101, 2021). "Thus, the overall findings of our study conclude that CHSY1-mediated CS may promote CD44 activity and consequently regulate integrin expression in glioma cells, thereby serving as a potential pathway for therapeutic targeting in glioma." (PMID 34944101, 2021). "Furthermore, C6S-p treatment also resulted in the suppression of ITGB1 mRNA expression in glioma cells as compared to non-treated glioma cells, which is consistent with the effects of CHSY1 silencing using specific siRNAs." (PMID 34944101, 2021).
brachydactyly syndrome (4 papers, 2017 to 2025). "In humans, loss of CHSY1 causes Temtamy preaxial brachydactyly syndrome, of which major features include limb malformations, short stature, and delayed motor and mental development." (PMID 41062067, 2025).
brachydactyly (3 papers, 2012 to 2025). A disease characterized by the presence of brachydactyly, including syndromic and non-syndromic forms. "Loss of function mutations of CHSY1 have been identified in human brachydactyly." (PMID 22952769, 2012).
clear cell renal cell carcinoma (3 papers, 2020 to 2023). "LINC01094 is proved to be a ceRNA for miR-224-5p in clear cell renal cell carcinoma, and it increases the translation of oncogene CHSY1 via competitively binding to miR-224-5p." (PMID 33069244, 2020). "Besides, LINC01094 could promote clear cell renal cell carcinoma development through the miR-224-5p/CHSY1 regulatory axis." (PMID 34819945, 2021).
Myeloma (2 papers, 2020 to 2024). "Myeloma-osteoclast interactions upregulate Chondroitin synthase 1 (CHSY1), triggering Notch signaling and boosting tumor cell proliferation and bone resorption." (PMID 39087026, 2024). "Myeloma-osteoclast interaction also upregulates Chondroitin synthase 1 (CHSY1), which induces Notch signaling promoting the survival of myeloma cells." (PMID 33634031, 2020).
amelogenesis imperfecta (1 paper, 2021). Amelogenesis imperfecta (AI) represents a group of developmental conditions affecting the structure and clinical appearance of the enamel of all or nearly all the teeth in a more or less equal manner, and which may be associated with morphologic or biochemical changes elsewhere in the body. "Even if few features are typical for some disorders, characteristic hand anomalies in CANT1, IMPAD1, CHSY1, and TGDS-related conditions or amelogenesis imperfecta in dysplasia due to mutations in SLC10A7, for example, may help clinicians to orientate the clinical diagnosis." (PMID 34220933, 2021).
atherosclerosis (1 paper, 2021). A disease characterized by the build-up of fatty material and calcium deposition in the arterial wall resulting in partial or complete occlusion of the arterial lumen. "The current results demonstrated thatET-1 enhanced CHSY1 level expression in VSMCs.Also, EGF and TGF-β, both which are known to beinvolved in the atherosclerosis development, up-regulatesCHSY1 level." (PMID 34837677, 2021).
chondrodysplasia (1 paper, 2017). "Knockdown of CHSY-1 by small interfering RNA (siRNA) causes a decrease in the number and molecular weight of CS chains, and CHSY-1 null mice exhibit chondrodysplasia and defects in chondroitin sulfation balance." (PMID 28514734, 2017).
developmental delay (1 paper, 2020). "For example, EXTL3 and CHSY1 mutations, which affect heparan sulfate and chondroitin sulfate synthesis, respectively, cause developmental delay and intellectual disabilities." (PMID 32001716, 2020).
endometritis (1 paper, 2022). An acute or chronic, usually bacterial infectious process affecting the endometrium. "Compared with the control group, circ-Chsy1, circ-Gm49339, mmu_circ_0001853 were significantly overexpressed (p < 0.01), and circ-Vps54 and mmu_circ_0000668 were significantly underexpressed in the endometritis group (p < 0.01)." (PMID 35744807, 2022).
intestinal cancer (1 paper, 2024). "Recent findings underscore the role of CHSY1 in depleting CD8+ T cells through succinate metabolism activation and the PI3K/AKT/HIF1A pathway, facilitating liver metastasis in intestinal cancer." (PMID 38812506, 2024).
nonsyndromic hearing impairment (1 paper, 2014). "In the human pathway of GAG and PG biosynthesis a gene-phenotype relationship is known for DFNA5 (hereditary nonsyndromic hearing impairment) and for CHSY1 (temtamy preaxial brachydactylyl syndrome)." (PMID 24586965, 2014).